CCL2 (C-C motif chemokine ligand 2)
Diseases named in the same sentence as CCL2 in open-access papers (continued):
Sharing a sentence is not in itself a finding about the gene and the disease.
viral infection (continued). "The comparable transcript levels of CXCL10, CCL2, and BCL2, as well as viral loads were observed between control and rIL-22-treated groups, indicating that IL-22 was dispensable for the growth, activation, and viral infection of human glial cells." (PMID 32843067, 2020). "Furthermore, while certain genes were repressed during both virus infections (e.g., Irf7 or Ifnb1), expression of others was more prominently reduced upon H5N1 infection (e.g., IL-1β, IL-6, Ccl2)." (PMID 32231671, 2020). "In separate publications a group in Hong Kong reported that elevated levels of IL-6, CXCL8, CCL2, and sTNFR-1 correlated with severe cases of A(H1N1)pdm09 virus infection overall and, in particular, with the extent and severity of influenza-associated pneumonia." (PMID 23468921, 2013). "Meanwhile, ARND also downregulated the levels of mRNA expression of proinflammatory transcription factors (NF-κB and c-Rel), proinflammatory cytokines (IL-1β, IL-6, TNF-α and CCL2) and NOS2 in vitro, which may be useful to attenuate the inflammatory response upon viral infection." (PMID 35897044, 2022). "Cytokines associated with lung injuries, such as IL-1 and TNF-α could induce the production of several chemokines, such as CCL2, CCL3, CCL5, and CXCL8, culminating in a cytokine-to-chemokine-to-cytokine signaling cascade through inflammatory response to the viral infection." (PMID 36685603, 2022). "Retinoic acid-inducible gene I (RIG-I) plays a role in mediating the up-regulation of CCL2 expression by mouse microglia in response to viral infection but it is not known whether RA would have the same effect." (PMID 34739478, 2021). "Furthermore, we observed elevated levels of CXCL8 and CCL2 that promote the recruitment of non-adaptive immune cells to the liver such as monocytes, the main source of IL-15 and IL-18 during viral infections." (PMID 33617602, 2021). "One of the models used to study viral infection of microglia in vitro is through the use of human peripheral blood monocytes, which can differentiate into monocyte-derived microglia after culture with a serum-free medium containing M-CSF, GM-CSF, NGF, and CCL2." (PMID 34916908, 2021). "Similarly, the CSF of the fetus had significantly elevated levels of IL-1RA, Eotaxin (CCL-11), MCP-1 (CCL-2) and IP-10 (CXCL-10) compared to the maternal CSF (p < 0.05, one-way ANOVA), which could be indicative of an ongoing viral infection." (PMID 29343712, 2018). "As part of the innate immune response against virus infections targeting the respiratory tract, such as influenza virus or RSV infection, JEV infection of porcine NEC also induced several chemokines (CCL2, CCL5, and CXCL10), which would direct the migration of monocytes to the site of infection." (PMID 30282716, 2018). "Additionally, PDCoV infection increased the transcription of the chemokines CCL2, CCL4, CXCL9, CXCL10 and CXCL11, suggesting that these chemokines may contribute to the recruitment and regulation of macrophages or other inflammatory cells to the sites of virus infection." (PMID 35328701, 2022). "As a consequence, levels of pro-inflammatory cytokines and chemokines, such as IL-1β, Il-6, IL-12, CCL2 and CCL3 increased within 24 hours of CL, but not PBS treatment, prior to virus infection." (PMID 19851468, 2009). "However, we detected no further induction of IFN-α after virus infection despite a surge of pro-inflammatory responses (IL-6, IL-1β, TNF-α, IFN-γ CCL2, CCL3, and CXCL10) compared to mature hamsters." (PMID 37122119, 2023).
diabetic nephropathy (175 papers, 2008 to 2026). "CCL2 rs1024611 is associated with gestational diabetes, diabetic retinopathy and diabetic nephropathy." (PMID 36674502, 2023). "In a mouse model of streptozotocin-induced diabetic nephropathy, CCL2/MCP-1 deficiency suppressed renal injury by markedly reducing interstitial macrophages accumulation." (PMID 35732633, 2022). "After meta-analysis, 2 genetic variants- rs833061 in the VEGFA gene and rs3917887 in the CCL2 gene showed the most significant association with risk of diabetic nephropathy." (PMID 25280384, 2014). "rs833061 [OR 2.08 (95% CI 1.63-2.66)] in the VEGFA gene and rs3917887 [OR 2.04 (95% CI 1.64-2.54)] in the CCL2 gene showed the most significant association with the risk of diabetic nephropathy." (PMID 25280384, 2014). "In this meta-analysis, the insertion at CCL2 rs3917887 showed two fold higher risk of diabetic nephropathy as compared to controls." (PMID 25280384, 2014). "However, it was also reported that SphK1 deficiency results in CCL2 reduction and prevention of renal fibrosis in diabetic nephropathy." (PMID 28282921, 2017). "Similarly, deleting CCL2, which encodes monocyte chemoattractant protein-1, attenuated renal tubule cell damage, and suppressed development of diabetic nephropathy in streptozotocin (STZ)-treated mice." (PMID 28149671, 2016). "Our study identifies COL1A2, CD163, FN1, and CCL2 as key molecular signatures involved in the immunoinflammatory and fibrotic progression of diabetic nephropathy." (PMID 40969366, 2025). "In conclusion, our study identifies COL1A2, CD163, FN1, and CCL2 as key molecular players involved in fibrosis, immune activation, and inflammatory signaling in diabetic nephropathy." (PMID 40969366, 2025). "In contrast, CCL2 was overexpressed in lupus nephritis (p < 0.0001, Fold Change: 2.294), diabetic nephropathy (p < 0.0001, Fold Change: 3.466), focal segmental glomerulosclerosis (p < 0.01, Fold Change: 3.171), and minimal change disease (p > 0.05)." (PMID 35464092, 2022). "ALPK1 was therefore determined to be a mediator involved in diabetic-nephropathy-induced upregulation of CCL2 and CCL5 chemokines." (PMID 36139553, 2022). "It has also been reported that an increased expression of CCL2 in the mesangial cells can stimulate collagen deposition, extend the mesangial matrix, and mediate collagen deposition and fibrosis in diabetic nephropathy." (PMID 35706905, 2022). "Various inflammatory stimuli, such as TNF-α, CCL-2, IL-1β, and IL-6, which drive chronic renal inflammation in diabetic kidney disease, have been shown to stimulate Saa3 production in mice." (PMID 35055081, 2022). "ALPK1 is a mediator of CCL2 and CCL5 chemokine, and upregulation of NF-κβ is associated with the induction of diabetic nephropathy." (PMID 36139553, 2022). "Genetic knockdown and pharmacologic inhibition of MCP-1/CCL2 already demonstrated to attenuate inflammation, tubulus atrophy, albuminuria, and progressive fibrosis in several animal models of diabetic and non-diabetic kidney disease." (PMID 33728540, 2021). "Several reports have described the involvement of the CCL2/CCR2 axis in the final common pathway in animal models of diabetic kidney disease, and inhibitors of the CCL2/CCR2 axis were effective in ameliorating CKD conditions in these models." (PMID 33159802, 2021). "In streptozotocin-treated mice, which is a rodent model for insulin deficient type 1 diabetes, high glucose increased the expression of renal CCL2 and CCL5, which was associated with the induction of diabetic nephropathy." (PMID 33207809, 2020). "Beyond its beneficial effects in DKD, the blockade of the MCP-1/CCL2 axis has demonstrated nephroprotective potential in a mouse model of non-diabetic kidney disease." (PMID 33139635, 2020). "CCX140-B, an inhibitor of the CCR2 receptor for CCL2, and the CCL2 inhibitor emapticap pegol were among the most promising drugs for diabetic kidney disease in phase II RCTs." (PMID 28333114, 2017).
diabetic nephropathy (continued). "Increased amounts of CCL2 have been detected in renal biopsies and urine from patients with diabetic nephropathy, and CCL2 has been shown to be a marker of late stage diabetic nephropathy." (PMID 25973922, 2015). "In this meta-analysis, variants within or near VEGFA (two variants), CCR5 (two variants), CCL2, IL-1, MMP9, EPO, IL-8, ADIPOQ and IL-10 were significantly associated with diabetic nephropathy." (PMID 25280384, 2014). "Recent studies have suggested a beneficial effect of blocking the action of CCL2 on diabetic nephropathy and renal function through anti-fibrotic effects." (PMID 22817530, 2012). "The CCL2, IL8, CCR5 and MMP9 polymorphisms were found to be associated with the risk of diabetic nephropathy." (PMID 19357773, 2009). "Targeting MCP-1/CCL2/CCR2 was also protective in experimental diabetic nephropathy." (PMID 34307414, 2021). "Clinical data may however suggest that rather CCL2 (MCP-1), if any single cytokine, is mechanistically required in diabetic kidney disease, at least in humans." (PMID 34009468, 2021). "Our previous study has also demonstrated that CCL2/CCR2 signaling axis might be a potential therapeutic target in diabetic kidney disease through improving podocyte permeability, actin cytoskeleton, and podocyte motility." (PMID 31498850, 2019). "In human and experimental models, CCL2 contributes to a variety of renal diseases, including progressive renal damage such as chronic rejection of renal transplantation, lupus nephritis, lgA nephropathy, and diabetic nephropathy." (PMID 31498850, 2019). "Although these studies provide some indication that anti-inflammatory strategies targeting the MCP-1/CCL2 or the JAK–STAT pathway may be a fruitful approach to delay the progression of diabetic kidney disease, many questions remain unanswered." (PMID 27338625, 2016). "More importantly, in addition to its role as a mediator of monocyte recruitment, recent studies on both experimental and human diabetic nephropathy have shown that the CCL2/CCR2 system plays a pathological role in the depletion of podocytes and the development of proteinuria." (PMID 25807547, 2015). "The key finding of our study was that polymorphisms in IL8, CCL2, CCR5, and MMP9 genes were associated with increased risk of nephropathy in Asian Indian type 2 diabetics and co-occurrence of specific risk genotypes of these genes conferred several fold greater risk of diabetic nephropathy." (PMID 19357773, 2009). "In patients with diabetic nephropathy, MRA reduces the upregulation of pro-inflammatory mediators, including TGF-β, PDGF,CCL2 and so on." (PMID 37538798, 2023). "We first identified the expression level of CCL2, FOS, JUN in IgAN, lupus nephritis, diabetic nephropathy, focal segmental glomerulosclerosis, minimal change disease, and membranous glomerulonephropathy, respectively." (PMID 35464092, 2022). "A number of CCL2/CCR2 axis inhibitors, such as CCX140-B and emapticap pegol, have also been developed, and have demonstrated a degree of clinical benefit for diabetic kidney disease in humans." (PMID 33159802, 2021). "Recently, phase 2 studies of certain inhibitors of the CCL2/CCR2 axis, such as CCX140-B and emapticap pegol, have been conducted in diabetic kidney disease patients." (PMID 33159802, 2021). "Several reports have shown that the activation of macrophage induction through the CCL2/CCR2 axis particularly induces injury to the nephron and renal tubes in CKDs, such as glomerulonephritis and diabetic kidney diseases." (PMID 33159802, 2021). "CCL-2 is a chemokine which attracts monocytes into the tubulointerstitial space after IRI and mediates fibrosis in IgA nephropathy and diabetic nephropathy." (PMID 32059667, 2020). "ALPK1 is a mediator for CCL2 and CCL5 chemokine up‐regulation involving in diabetic nephropathies induction." (PMID 31557402, 2019).
diabetic nephropathy (continued). "Our data suggest that ALPK1 is a potential mediator for CCL2 and CCL5 chemokines induction involving in ALPK1‐mediated accelerated diabetic nephropathies." (PMID 31557402, 2019). "The involvement of the renin-angiotensin-aldosterone system, chemokines such as monocyte chemoattractant protein-1 (MCP-1)/CCL-2, transforming growth factor-β1 (TGF-β1) and advanced glycation end products in diabetic nephropathy has been reported." (PMID 25255225, 2014). "CCL2, also known as Monocyte chemo-attractant protein-1(MCP-1), is the strongest known chemo-tactic factor for monocytes and is upregulated in diabetic nephropathy." (PMID 25280384, 2014). "DDIT3, GADD45A, THBS2, CCL2, and CSF1R showed consistent expression trends across platforms, and are known mediators of inflammation, extracellular matrix remodeling, and stress responses in diabetic kidney disease." (PMID 41481573, 2026). "CCL2 is a key chemokine in monocyte recruitment, and inhibitors of the CCL2–CCR2 axis (e.g., bindarit, CCX872) have demonstrated renoprotective effects in diabetic kidney disease by reducing macrophage infiltration and inflammation." (PMID 40969366, 2025). "Basal and IL-1β-mediated expression of MCP-1/CCL2, a cytokine that is involved in early “inflammatory” pathogenesis of diabetic and non-diabetic kidney disease as well as cellular response to LPS, was inhibited by Empa at the mRNA and protein level in both HPTC lines." (PMID 33728540, 2021).
lung carcinoma (168 papers, 2007 to 2026). "CCL2 secreted from mast cells exhibits proinflammatory and chemotactic properties and is associated with tumor angiogenesis in lung cancer." (PMID 39764562, 2025). "CCL2 also acts directly on lung cancer; blocking CCL2 enhanced the susceptibility of A549 cells of the lung cancer cell line to docetaxel." (PMID 34445235, 2021). "rs3760396 G/C polymorphism of CCL2 was genotyped using PCR in 394 patients with lung cancer and 545 cancer-free controls from the same Northeast region of China." (PMID 27145753, 2016). "We summarized genotype distribution and allele frequency of rs3760396 SNP in CCL2 gene in controls and lung cancer cases." (PMID 27145753, 2016). "In current study, we genotyped CCL2 rs3760396 polymorphism in a total of 939 Han-ancestry Chinese subjects, including 395 patients with lung cancer and 545 healthy controls." (PMID 27145753, 2016). "Moreover, CCL2 overexpression was shown to be associated with poor prognosis of lung cancer, esophageal cancer, hepatocellular carcinoma, glioblastoma multiforme, and diffuse large B-cell lymphoma." (PMID 40343498, 2025). "Additionally, NF-κB-mediated upregulation of CCL2 promoted the infiltration of tumor-associated macrophages and tumorigenesis in lung cancer." (PMID 37865804, 2023). "An effect of pevonedistat on tumor-associated macrophage recruitment was shown in the lung cancer metastasis model, and the mechanism was mediated by a reduced expression of a macrophage chemotactic cytokine, C-C motif chemokine ligand 2 (CCL2), in tumor cells." (PMID 33233664, 2020). "In conclusion, our data showed that miRNAs-mediated FOXO3a/VEGF/CCL2 signaling plays a prominent role in transforming NFs into CAFs, thus providing further support for the development of new diagnostic and therapeutic approaches to lung cancer." (PMID 27541266, 2016). "The association between genetic polymorphism in CCL2 and lung cancer is biologically plausible." (PMID 27145753, 2016). "Our current study sought out to study whether the same single nucleotide polymorphism (SNP: rs3760396) of CCL2 is also associated with the occurrence of lung Cancer and its pathological subtypes in a Chinese population." (PMID 27145753, 2016). "Chemokine-driven immunosuppression is exemplified in KRAS-mutant lung cancer, where senescent cells recruit MDSCs and regulatory Tregs via CCL2 secretion, establishing an immune-privileged niche." (PMID 40510156, 2025). "A previous study highlighted that the reciprocal communication between TAMs and lung cancer cells through the CCL2/CCR2 signaling pathway is a significant mechanism underpinning TAM-driven facilitation of lung cancer proliferation and dissemination." (PMID 40417000, 2025). "TLR2 enhances lung cancer cell migration and invasion by promoting the expression of CCL2, IL-6, and MMP-2 through the cAMP-AMPK-TAK1 signaling axis." (PMID 41293166, 2025). "In summary, these findings show DT as a potential candidate for lung cancer therapy by disrupting macrophage-cancer cell crosstalk and suppressing key cytokines like CCL2." (PMID 40417000, 2025). "In KRAS-mutant lung cancer, senescent macrophages secrete CCL2 to recruit MDSCs, while IL-10 and TGF-β polarize tumor-associated macrophages (TAMs) toward an immunosuppressive M2 phenotype, crippling cytotoxic T cell activity." (PMID 40510156, 2025). "Concurrent studies, like that by Lei Li and colleagues, have shown high CCL2 levels in the tumor microenvironment as predictors of survival in lung cancer patients." (PMID 38962009, 2024). "We also validated the expression of metastatic genes in lung cancer tissues and analysed the correlation between CCL2 and metastasis." (PMID 37850256, 2024). "We found that the expression of up‐regulated hub DEAMGs BCL2L1, CASP8, SIRT1 and CCL2 in lung cancer tissues with high metastasis was dramatically increased compared with lung cancer tissues with low metastasis." (PMID 37850256, 2024).